SCAT8 (S-phase cancer associated transcript 8)
Synonyms: EYS-AS1
Gene: Long non-coding RNA gene on chromosome 6 (63,805,797 to 63,822,975, forward strand). Ensembl gene ENSG00000236345.
Diseases named in the same sentence as SCAT8 in open-access papers:
SCAT8 is named in the same sentence as 2 diseases in open-access papers, as found by Europe PMC text mining. Sharing a sentence is not in itself a finding about the gene and the disease. The quoted sentences say what the papers report.
nasopharyngeal carcinoma (2 papers, 2023). A carcinoma arising from the nasopharyngeal epithelium. "Through analysis, a regulatory network was discovered that involved SCAT8/miR-125b-5p axis and contributed to the malignant progression of nasopharyngeal carcinoma by inducing SCARB1 expression." (PMID 37628612, 2023). "Our findings indicated that the SCAT8/miR-125b-5p axis promoted the malignant progression of nasopharyngeal carcinoma by driving the expression of SCARB1." (PMID 37009875, 2023). "Moreover, as a ceRNA of miR-125b-5p, SCAT8 can not only regulate the expression of SCARB1, but also regulate the malignant progression of nasopharyngeal carcinoma." (PMID 37009875, 2023).
cancer (1 paper, 2018). A tumor composed of atypical neoplastic, often pleomorphic cells that invade other tissues. "For instance, SCAT8 appeared to be the top prognostic indicator in our studies with the higher hazard ratio in our multivariate models and it also interferes with cancer cell hallmarks, indicating that it may be an oncogenic driver in multiple cancers." (PMID 29491376, 2018). "Thus, our functional and clinical investigations on SCAT8, SCAT5, and SCAT1, suggests that our cell cycle-based functional screen indeed has identified potential lncRNA-based cancer drivers." (PMID 29491376, 2018).